GCG (glucagon)
Diseases named in the same sentence as GCG in open-access papers (continued):
Sharing a sentence is not in itself a finding about the gene and the disease.
Hypoglycemia (continued). "In addition, knockdown of GLUT2 transporter in the hypothalamic area has shown to decrease feeding and body weight gain, suppress the insulin response triggered by intracarotid glucose injection and reduce the glucagon secretion in response to insulin-induced hypoglycemia." (PMID 32232085, 2018). "Notably, a recent study demonstrated that the patients with pancreatitis had reduced secretion of glucagon which might account for hypoglycemia." (PMID 28249585, 2017). "Compared to β-cell factors, a conceptual advantage of somatostatin-mediated glucose inhibition of glucagon release is that it may operate also in hypoglycaemia, since glucose stimulates somatostatin release from mouse and human islets at similar concentrations that inhibit glucagon secretion." (PMID 27044660, 2016). "A question, important for the safety of the patients in whom scintigrapy with labelled GLP-1 analogue is performed, has been raised whether the GLP-1 peptide, similarly to a native GLP-1, may disturb hypoglycemia counterregulation by suppression of glucagon secretion." (PMID 27526057, 2016). "GLP-1-based diabetes therapies affect glucose control through several mechanisms, including slowed gastric emptying, regulation of postprandial glucagon, reduction of food intake, and enhancement of glucose-dependent insulin secretion without the risk of hypoglycemia." (PMID 25785276, 2015). "This work aimed at investigating whether liver glucose release and its stimulation by adrenaline and glucagon could explain the change in the profile of the insulin-induced hypoglycaemia observed in vivo in food-restricted rats subjected to an acute exercise session." (PMID 24719616, 2014). "Thus, proper nutrition, including the digestion of complex carbohydrates to avoid hypoglycemia that results in increased glucagon levels, may be a critical component of novel anti-HBV therapeutic strategies." (PMID 24529027, 2014). "Less hypoglycemia, as shown in the study by Fonseca, could be a result of an improved alpha cell function, which has been described not only postprandial (reduction in glucagon) but also during the reaction after induced hypoglycemia when a slightly increased increment of glucagon was seen." (PMID 25175981, 2014). "While it remains ill-defined whether low glucose directly stimulates glucagon release during hypoglycemia, the paracrine/endocrine (interstitium/microcirculation) inhibitory effects of insulin and somastostatin on glucagon secretion are relatively well established." (PMID 25177371, 2014). "An alternative explanation for hypoglycemia could be compromised glucagon function." (PMID 23977255, 2013). "Moreover, glucagon secretion responds normally to hypoglycemia after denervation of the pancreas." (PMID 24315372, 2013). "Presumably, under insulin-stimulatory conditions, intra-islet insulin action may not be able to efficiently exert suppressive effects on α-cell secretion, whereas under glucagon-stimulatory conditions, intra-islet hyperinsulinemia prevents the glucagon response to hypoglycemia." (PMID 23316165, 2012). "Moreover, αIRKO mice displayed an abnormal glucagon response to hypoglycemia." (PMID 22479612, 2012). "Neither approach to disruption of GCGR function results in overt hypoglycemia; this suggests that pharmacotherapy aimed at antagonizing glucagon action at the GCGR may provide useful reductions in blood glucose without significantly increasing risk for hypoglycemia." (PMID 23185367, 2012). "Therefore, persistent suppression of glucagon secretion by exogenous insulin impairs the insulin-glucagon fine-tuning system that predominantly maintains glucose homeostasis, and may result in iatrogenic hypoglycemia." (PMID 23316165, 2012). "Therefore, glucagon is an effective therapy for treating severe hypoglycemia in humans." (PMID 23316165, 2012).
Hypoglycemia (continued). "RCTs with a duration of ≥ 4 weeks were deemed eligible for the incidence of severe hypoglycemia, time-in-range (TIR), total insulin dose (TID), change in C-peptide, and glucagon levels." (PMID 40760325, 2025). "During experimentally-induced hypoglycemia, obese PCOS patients exhibited three-fold greater glucagon secretion than BMI-matched controls." (PMID 40013621, 2025). "Conventional medical therapies for glycemic control demonstrate limited efficacy in NICTH: intravenous glucose provides only transient relief, and glucocorticoids, glucagon, GH, or somatostatin analogs often fail to suppress IGF-2-mediated hypoglycemia." (PMID 41367853, 2025). "Our patient had hypoglycaemia (2.25 mmol/L), suppressed insulin (< 1.2 pmol/L), low C‐peptide (0.040 mcg/L), and reduced IGF‐I (5.51 mcg/L), with a positive glucagon stimulation test—all consistent with NICTH." (PMID 40697895, 2025). "Furthermore, hypoglycemia is associated with high expression of the receptor for advanced glycation end products (RAGE) in T1D adolescent donors compared to non-diabetic adolescent donors, with AGER being the most important predictor of the islet’s glucagon levels." (PMID 39594662, 2024). "In response to strong allostatic challenges, such as hypoglycemia, the CNS coordinates the CRR to promote glucagon release and suppress insulin secretion, which augments glycogenolysis and gluconeogenic capacity." (PMID 38826340, 2024). "Dual-hormone CLS delivering insulin and glucagon or insulin and the amylin analogue, pramlintide, aim to more closely imitate pancreatic glucose control physiology and may improve performance with regards to managing postprandial glucose excursions and exercise-induced hypoglycemia." (PMID 39390689, 2024). "However, this activity decreases in patients with chronic liver disease; thus, continuous glucagon infusion might be favorable as a treatment for hypoglycemia caused by non-islet cell tumor." (PMID 38953327, 2024). "A next-generation glucagon analog, dasiglucagon, was approved by the FDA in 2021 for the treatment of severe hypoglycemia in T1D individuals ≥6 years of age." (PMID 39944479, 2024). "Collectively these responses in the SSTR2 antagonist-treated animal groups resulted in glucagon levels greater than in T2D controls and similar to those observed in HFF control response to hypoglycemia." (PMID 38510652, 2024). "Therefore, glucagon, through attenuation of hypoglycemia, may prevent AD neuropathology." (PMID 38977507, 2024). "All patients were educated on dietary modification, hypoglycemia prevention and treatment, and glucose monitoring with SMBG as well as CGM and were prescribed glucagon." (PMID 39330031, 2024). "However, if glucagon can be used not only to prevent and treat hypoglycaemia but primarily to improve the performance of SC CGM and SC absorption of insulin, this new, innovative and disruptive use of glucagon may fulfil the dream of a true, fully automated AP suitable for most patients with DM1." (PMID 37715091, 2024). "There are several tests used for CAI detection: LDAT, metyrapone test, insulin-induced hypoglycemia test (IIHT), glucagon stimulation test (GST), and corticotrophin hormone (CRH) stimulation test." (PMID 38994010, 2024). "Without restoring glucagon counterregulation to hypoglycemia in T1D and advanced T2D, strategies for improving glycemic control, including the use of newer insulin analogues and continuous glucose monitoring, fail to eliminate the risk of clinically significant hypoglycemia." (PMID 38298268, 2023). "The other study was an overnight study showing that the addition of glucagon significantly improved TIR and reduced the time in level 1 hypoglycemia, but had similar time in level 2 hypoglycemia when compared with SH." (PMID 36755913, 2023).
Hypoglycemia (continued). "Thus, we may suggest that BPC 157 recovered both insulin pathways (insulin and glucagon release are under KATP channel control as well as under the control of hypothalamus-brain stem hypoglycemia-induced vagal signaling) during hypoglycemia and regained brain–gut function integrity." (PMID 37242459, 2023). "In summary, our data demonstrate that when compared with consumption of a normal breakfast and lunch, fasting for approximately 22 hours decreased hepatic glycogen content and lowered glucagon and EGP during insulin-induced hypoglycemia." (PMID 37166980, 2023). "Thus, in the setting of impaired insulin and glucagon responses to hypoglycemia, recurrent hypoglycemia induces a syndrome of Hypoglycemia Associated Autonomic Failure (HAAF) that is composed of an impaired awareness of hypoglycemia (IAH) and a blunted counterregulatory response." (PMID 37942482, 2023). "Glucose activates glucagon secretion in isolated rat and mouse α-cells, as well as seemingly having no impact on clonal mice α-cells, which might be opposite of the prevailing view of glucagon as a key counterregulatory hormone that prevents hypoglycemia by increasing hepatic glucose output." (PMID 37645413, 2023). "Glucose, C-peptide and glucagon levels in response to MMCT in patients with FCPD and hypoglycemia awareness / unawareness." (PMID 35819935, 2022). "By contrast, under hypoglycemia status, the GRS glucagon MN patch treated group showed notably higher PGLs, which reached and maintained in the normal range 3‐h post‐administration." (PMID 35957510, 2022). "SSR149415 treatment abolished insulin-induced glucagon secretion, showing that intact AVP/V1bR signaling is required for efficient glucagon release following insulin-induced hypoglycemia." (PMID 34752420, 2021). "In α-cells, defective counter-regulation to hypoglycemia in T1DM and inappropriate postprandial glucagon release in T2DM are observed." (PMID 33494193, 2021). "Insulin-induced hypoglycemia enhances population activity of AVP neurons in the supraoptic nucleus (SON), driving glucagon secretion AAV-DIO-hM3Dq-mCherry was injected bilaterally into the SON of Avpires-Cre/+ mice." (PMID 34787082, 2021). "There were also concomitant decreases in circulating insulin and increases in glucagon, typical of the counter-regulatory response (CRR) to hypoglycemia." (PMID 34265067, 2021). "Hypoglycaemia was severe with a mean Glucose Infusion Rate (GIR) of 14 mg/kg/min and 15 (60%) patients requiring additional intravenous glucagon to maintain glycaemic stability." (PMID 32256453, 2020). "The physiological relevance of GIP-stimulated glucagon during hypoglycemia is unclear, since GIP is secreted in response to nutrients and is expected to be at low levels during hypoglycemia." (PMID 32964214, 2020). "That is, slow-onset hypoglycemia is primarily sensed by the PMV and information is sequentially relayed to the hindbrain catecholamine neurons and hypothalamus in order to increase glucagon and epinephrine secretion." (PMID 29593556, 2018). "In addition, our hypothesis is supported since the insulin/glucagon ratio proved to be positive after the treatments, contributing to ameliorate the hyperglycemic state while it also maintains normal glucagon levels, and protects from hypoglycemia." (PMID 30333575, 2018). "The number of hypoglycemia events requiring CHO treatment were also reduced (3 in DH-AP vs. 15 in SH-AP), all showing an added benefit of glucagon in AP during exercise." (PMID 30713524, 2018). "Increased glucose uptake, lower insulin and glucagon secretion, decreased lipolysis and liver gluconeogenesis are some effects of the massive secretion of IGF2 that lead to hypoglycemia." (PMID 27134683, 2016). "Beyond this paracrine regulation, glucagon secretion is influenced by autonomic factors originating in brain, where the ventromedial hypothalamus (VMH) is recognized as an important hypoglycemia-sensing area that can modulate glucagon release." (PMID 25177371, 2014).
Hypoglycemia (continued). "In addition, if hypoglycemia persists for more than two hours, there is an increase in the blood concentration of cortisol and growth hormone and the combination of glucagon, epinephrine, cortisol, and growth hormone could overcome the inhibitory effect of insulin on LGP." (PMID 24062772, 2013). "In the face of hypoglycaemia, infants with CHI have inappropriately elevated serum insulin, low ketone bodies, low fatty acids and show a glycaemic response to glucagon." (PMID 24616771, 2013). "A low incidence of hypoglycemia is observed with the GLP-1R agonists and DPP-4 inhibitors, likely because of their glucose-dependent actions on insulin and glucagon secretion." (PMID 22390369, 2012). "Collectively, our findings show that supraphysiological levels of GLP-2 slightly but significantly increase glucagon secretion during euglycemia and not during insulin-induced hypoglycemia or hyperglycemia, in lean, young, healthy men." (PMID 41541287, 2026). "Compared to placebo, GLP-2 increased glucagon secretion slightly during euglycemia, and not during insulin-induced hypoglycemia or hyperglycemia." (PMID 41541287, 2026). "In summary, in a rat model of insulin-treated T2D, daily SSTR2a administration increased glucagon counterregulation to hypoglycemia without worsening overall insulin sensitivity or glycemic control." (PMID 41502124, 2026). "The purpose of this study was to assess the effects of daily SSTR2a administration for up to 11 days on overall glycemia and glucagon responses, in a male rat model of insulin-treated T2D, with and without hypoglycemia." (PMID 41502124, 2026). "Exogenous GLP-2 increased glucagon secretion slightly during euglycemia and not during insulin-induced hypoglycemia or hyperglycemia in healthy young men." (PMID 41541287, 2026). "Previous studies have demonstrated a potential advantage of using glucagon in fasting—induced hypoglycemia, children and during exercise, yet this is the first real—world evaluation that presents data on using MDG for hypoglycemia in prolonged, repetitive fasting situations." (PMID 40364253, 2025). "Conversely, GIP enhances glucagon secretion, intensifies the postprandial glucagon response, and stimulates pancreatic alpha cells to produce glucagon during hypoglycemia or euglycemia, but not during hyperglycemia." (PMID 40649920, 2025). "She, however, reported an increase in post-prandial hypoglycemia, managed with simple carbs and not severe with no glucagon use." (PMID 39707844, 2025). "However, GIP enhances glucagon secretion during hypoglycaemia, while GLP-1 decreases glucagon during hyperglycaemia." (PMID 39762582, 2025). "Qualitative assessment of individual trials showed that addition of GLP-1RA does not prevent progressive C-peptide loss and that patients receiving a GLP-1RAs do not have inadequate glucagon secretion in response to hypoglycemia." (PMID 40760325, 2025). "Circulating glucagon is elevated at normoglycemia in T1D and not appropriately stimulated upon hypoglycemia." (PMID 41026524, 2025). "Newer ready-to-use glucagon products that are stable at room temperature offer improved convenience; however, they are manufactured for full-dose treatment of severe hypoglycemia and are not optimized for mini-dose use." (PMID 41510436, 2025). "In non-clinical settings, during severe hypoglycemia when the patient cannot consume glucose orally, the preferred route of injection of glucagon is SC or IM." (PMID 40585626, 2025). "Hypoglycemia is further exacerbated by IGF-2 binding to IGF-1R and IR at the pancreatic alpha cells and hypothalamus, which mimics the effects of insulin and IGF-1 to suppress secretion of counterregulatory hormones—glucagon and GH." (PMID 41179270, 2025). "Conversely, despite the preservation of the alpha-cells, individuals with T1D fail to secrete enough glucagon in the counterregulatory response to hypoglycemia when compared to non-diabetic individuals." (PMID 38612880, 2024).
Hypoglycemia (continued). "Within the first year of T1D, glucagon responses to hypoglycemia are blunted but epinephrine responses are not; defective and absent glucagon responses to hypoglycemia have been observed in PWD with significant residual endogenous β-cell function." (PMID 38894740, 2024). "Type 1 diabetic patients will exhibit an absent endogenous insulin response, in combination with a glucagon response to hypoglycaemia that is lost within 5 years of the onset of diabetes." (PMID 38392992, 2024). "A small, but non-significant increase in glucagon was also seen during next-day hypoglycaemia after a single bout of HIIT in our previous study." (PMID 38010533, 2024). "Relative to the pre-intervention results, there was an increase in plasma glucagon during hypoglycaemia following RT-CGM+HIIT, but not RT-CGM (RT-CGM vs RT-CGM+HIIT: 1 vs 16 ng/l, p=0.01)." (PMID 38010533, 2024). "The incidence of hypoglycemia after MVR was 14.2%, and plasma glucagon concentrations increased in these dogs (mean: 260 pg/mL and 644 pg/mL pre- and postoperatively, p < 0.001), whereas serum insulin concentrations decreased (median: 0.50 ng/mL and 0.29 ng/mL pre- and postoperatively, p = 0.002)." (PMID 38393097, 2024). "Mini- dose glucagon did not cause or worsen nausea or emesis, and none of the MDG-treated children required hospitalization due to hypoglycemia." (PMID 39944479, 2024). "Spontaneous hypoglycemia in the absence of insulin therapy following TPIAT is a recognized complication, which has been attributed to lack of protective glucagon responses to hypoglycemia, following intrahepatic islet autotransplantation." (PMID 39450137, 2024). "Hepatic glycogen content is much reduced in T1D mice, which explains why the CYN154806-induced elevation of glucagon does not ameliorate hypoglycaemia in these mice." (PMID 39313541, 2024). "Despite an overwhelming body of literature demonstrating that MDG is extremely safe and effective for the treatment of mild to moderate hypoglycemia in T1D, glucagon is not yet FDA approved for use in this manner for this indication." (PMID 39944479, 2024). "During hypoglycemia, SF-1 curbs hypoglycemic augmentation of glucagon and corticosterone secretion in the male, but does not exert this action in the female." (PMID 39401164, 2024). "This response is believed to be mediated by both branches; however, early-stage hypoglycemia (75–85 mg/dL) results in PSNS activation of pancreatic α-cell islets and subsequent glucagon secretion, although α-cell islets recruitment increases once FBG is below 100 mg/dL." (PMID 38837971, 2024). "In another study, administration of a fixed dose subcutaneous continuous infusion of glucagon for 4 weeks, did not improve epinephrine response to hypoglycemia in individuals with T1D and IAH." (PMID 38323079, 2024). "The newer formulations of glucagon, which do not require reconstitution and are stable at room temperature, are also meant to deliver a large dose of glucagon in the setting of severe hypoglycemia, and do not lend themselves to the creation of MDG aliquots." (PMID 39944479, 2024). "al. reported that ZnT8 is required for hypoglycemia induced glucagon secretion from α-cells in the islets without significantly affecting glucose tolerance in the α-cell-specific Znt8 KO mice." (PMID 39567934, 2024). "On the contrary, GLP-1 suppresses glucagon secretion in both healthy individuals and those with T2DM under normoglycemia and hyperglycemia but not during hypoglycemia, thereby reducing the potential for developing severe hyperglycemia or hypoglycemia." (PMID 39114288, 2024). "The suggested mechanism of action is the rapid decrease of elevated plasma glucose in response to glucagon mimicking a hypoglycaemia-like stimulus without absolute hypoglycemia." (PMID 38935296, 2024).